LIFR (LIF receptor subunit alpha)
Diseases named in the same sentence as LIFR in open-access papers (continued):
Sharing a sentence is not in itself a finding about the gene and the disease.
tumor (continued). "The role of LIF/LIFR autocrine signaling in tumor recurrence is substantial since following chemotherapy, residual CSCs might repopulate tumor once again utilizing positive autocrine loop without the need of paracrine factors from the host tissue." (PMID 38789520, 2024). "Furthermore, limited dilution and in vivo tumorigenic assays revealed that co‐administration of CAFs‐2 robustly promoted tumor formation and increased CSCs frequencies, but failed to induce similar effects in those LIFR‐depleted cancer cells." (PMID 39206755, 2024). "It was not the only pathway for GAS5, miR-21, and LIFR to inhibit the tumor cells, and one study reported that overexpression of GAS5 could inhibit cell proliferation and promote apoptosis by inhibiting miR-182-5p expression." (PMID 36062165, 2022). "However, because, in comparison with normal mucosa, the expression of Onecut2 mRNA was upregulated in the bulk tumor of patients with GC without peritoneal involvement but downregulated in those showing PC, we have focused our attention on LIFR." (PMID 35847866, 2022). "However, it remains unclear whether LIF in fact drives the metastasis suppressor actions of LIFR, since most data suggest that LIF is tumor-promoting." (PMID 32023849, 2020). "LIFr may or may not have effects on MMP2 mediated tumor progression depending on the cell types evaluated." (PMID 26329521, 2015). "Moreover, rational combination strategies, including LIFR inhibition with immune checkpoint blockade (e.g., anti–PD‐1/PD‐L1) or TAM reprogramming agents, may yield synergistic anti‐tumor effects, particularly in “cold” tumors with poor CD8+ T‐cell infiltration." (PMID 41163398, 2025). "Likewise, since bone marrow-resident cells express the gp130 subunit and many of the cytokine-specific receptors (e.g., LIFR and OSMR), the tumor cell production of these cytokines may also remodel the bone marrow microenvironment to make it more permissive for tumor colonization or dormancy." (PMID 32023849, 2020). "Together, these results demonstrate that co-targeting LIFR and MEK pathways using EC359 and trametinib provides superior anti-tumor efficacy in both xenograft and PDX models, without inducing observable toxicity, supporting its potential as a promising therapeutic strategy." (PMID 41154625, 2025). "LIF effects on metastasis were ablated through the shRNA knockdown of LIF in MDA-MB-231 cells, but given the absence of a functional LIFR in these cells, the effects observed in vivo would most likely be mediated through paracrine LIF signaling from the tumor cells to the microenvironment." (PMID 32023849, 2020). "The fact that both LIFR and LIF are overexpressed in NPC tumors derived from patients with metastasis implies that elevated cytoplasmic LIF in tumor cells may not originate from the microenvironment." (PMID 30504771, 2018).
cancer (86 papers, 2005 to 2026). A tumor composed of atypical neoplastic, often pleomorphic cells that invade other tissues. "LIF/LIFR signaling has been associated with proliferation, progression, metastases, stemness, and chemoresistance in several cancers." (PMID 40075639, 2025). "The LIF/LIFR axis has been implicated in several hallmarks of cancer, including enhanced proliferation, immune evasion, chemoresistance, and poor patient survival." (PMID 41154625, 2025). "The LIF (leukemia inhibitory factor)/LIFR (leukemia inhibitory factor receptor) cytokine signaling pathway has been linked to the progression of a variety of cancers; however, its importance in IBC has yet to be determined and was investigated in this study." (PMID 40075639, 2025). "Reports indicate that HDAC inhibitors can stimulate LIFR, leading to the acetylation of the LIFR promoter histone, thereby enhancing its expression and causing cancer cell proliferation while preserving dormancy, albeit with more intrusive effects." (PMID 40977686, 2025). "The LIF/LIFR axis is linked to cancer proliferation, immune system protection, chemoresistance, and patient survival." (PMID 39518071, 2024). "Analysis of cancer databases revealed that elevated expression of LIF or LIFR was associated with poor progression-free survival of OCa patients and a predictor of poor response to chemotherapy." (PMID 38789520, 2024). "Overall, LIFR was positively related to many kinds of cells in the microenvironment, including endothelial cells, cancer-associated fibroblasts, monocytes, mast cells and hematopoietic stem cells." (PMID 36925915, 2023). "Further, LIF/LIFR signaling in cancer cells has been linked to several oncogenic properties, including proliferation and cell survival, playing a role in immune system and chemoresistance." (PMID 38139260, 2023). "Experimental data describe the regulation of transcriptional activation at the LIFR promoter locus and indicate that the loss of PCBP1 expression induces FAM3C/LIFR-driven signaling that regulates transcriptional events associated with carcinoma pathology." (PMID 37927213, 2023). "The loss of LIFR enhances invasion and downregulates dormancy, quiescence, and cancer stem cell-associated genes." (PMID 30177834, 2019). "The significantly lower levels of LIFR expression in OAC patients with a poor response to neoCRT highlights the loss of LIFR as a predictive indicator of poor outcome, similar to findings in other cancers." (PMID 30263091, 2018). "Targeting LIF/LIFR might avoid side effects linked to pan-FGFRs inhibitor and might be a promising therapeutic strategy for the treatment of cancers with aberrant FGFR4 activation." (PMID 37945798, 2024). "Potentially, splicing events may occur to form isoform variants which may explain the dual LIFr specific bands we sometimes observed by Western blot and as seen in other cancers." (PMID 26329521, 2015). "This supports the notion that OSM could have opposing effects depending on which receptor it binds to initiate its signalling, with OSMR potentially being involved in the cancer-promoting role of the ligand, while association with LIFR could be linked to its growth-inhibitory effect." (PMID 34834425, 2021). "Thus, future work should determine whether downregulation or loss of LIFR plays a causal role in resistance to sorafenib-induced ferroptosis across multiple types of cancer." (PMID 34921145, 2021). "Multivariable analysis confirmed NBI as the strongest independent predictor of carcinoma, while epithelial LIF and LIFR expression showed inverse associations with histological malignancy and high-risk NBI vascular patterns." (PMID 41752061, 2026). "In this context, two LIFR antagonists are under development to treat cancers: the humanized anti-LIF antibody MSC-1 and the LIFR inhibitor EC359." (PMID 41562905, 2025). "LIFR activation inhibits cancer metastasis, while its downregulation activates YAP, promoting migration, invasion, and metastasis." (PMID 40977686, 2025).
cancer (continued). "Leukemia inhibitory factor (LIF) and its receptor (LIFR) play a major role in cancer stemness, progression, metastasis, and therapy resistance." (PMID 40804837, 2025). "The potential of inhibiting the LIF/LIFR axis for cancer treatment has been demonstrated using neutralizing antibodies or engineered ligand traps." (PMID 40075639, 2025). "Considering the significance of LIF/LIFR signaling in cancer, our team recently has created an inhibitor for LIFR, designated as EC359." (PMID 39518071, 2024). "In the present study, we report that the transcriptome analysis of cancer tissues from a cohort of locally advanced GCs express a dysregulated expression of LIF/LIFR and FGFR4." (PMID 37945798, 2024). "LIF/LIFR axis has been connected to numerous hallmarks of cancer, including proliferation, avoiding immune system damage, chemoresistance, and overall patient survival." (PMID 38789520, 2024). "LIFR methylation correlated significantly with gene expression at multiple probes in many cancer types." (PMID 36925915, 2023). "LIF and LIFR show an opposite modulation in the cancer tissues, thus while LIF expression is higher in PDAC in comparison with the adjacent normal tissue, the expression of LIFR is subject to opposite modulation." (PMID 36998446, 2023). "Clinically, the activation of the LIF/LIFR axis is correlated with poor prognosis and resistance to anti-cancer therapies." (PMID 36925915, 2023). "LIFR is expressed in a variety of organs and cell types and is involved in angiogenesis, cancer progression, development and regulation of stem cells." (PMID 36925915, 2023). "In summary, LIFR is a promising therapeutic target and prognostic biomarker for many cancer entities." (PMID 36925915, 2023). "LIF and LIFR, members of the interleukin-6 (IL-6) cytokine family, constitute a poorly-defined pathway connecting inflammation to cancer." (PMID 36925915, 2023). "Recently, increasing numbers of studies have been exploring the cancer type-specific role of LIFR in these cancers." (PMID 36925915, 2023). "Aberrant expression of LIFR in cancers and its prognosis ability, especially in UCEC was documented." (PMID 36925915, 2023). "Next, we determined the relationship between LIFR and immunoregulation-related genes, and saw clear correlations in most cancer types." (PMID 36925915, 2023). "The most relevant of which is that the role of LIF/LIFR system has been tested in in vitro models and therefore the real anti-cancer potential of BAR502 in PDAC should be further investigated in clinically relevant settings." (PMID 36998446, 2023). "To identify the mechanism of LIFR action in tumorigenesis and cancer progression, we explored targeting LIFR-interacting proteins and LIFR-expression related genes and performed functional enrichment analysis." (PMID 36925915, 2023). "LIF signalling in cancer cells is mediated by its binding to the LIFR complex and JAK/STA3 phosphorylation." (PMID 36359879, 2022). "Some of the defined target genes of LMNB1 like LIFR and IL6R are already reported to be cancer associated." (PMID 35883595, 2022). "The expression of gene LIF/LIFR is overexpressed in solid tumors, and plays an essential role in cancer metastasis, progression, and invasion." (PMID 36419120, 2022). "The LIF/LIFR signaling has been identified as a potential therapeutic target in the treatment of several cancers." (PMID 35847866, 2022). "Overall, there is abundant evidence of a metastasis-supressing role of LIFR, suggesting a systemic pro-dormancy role in cancer cells disseminated to distant sites." (PMID 34834425, 2021). "Described by others in the past as enigmatic and paradoxical, LIF and LIFR are expressed in a diverse array of cells in the body, and the narrative surrounding them in cancer-related processes has been vague, and at times even contradictory." (PMID 34395259, 2021).
cancer (continued). "LIFR influences the PI3K/AKT pathway in a variety of cancers including prostate, gastric, hepatocellular, nasopharyngeal and rhabdomyosarcomas." (PMID 34395259, 2021). "Further, CAFs regulate cancer stem cells through the LIF/LIFR pathway and can be an anticancer therapy target." (PMID 34947829, 2021). "Recently published studies indeed support oncogenic role of LIF/LIFR signaling in cancer progression." (PMID 34716410, 2021). "Leukemia Inhibitory Factor (LIF) and its receptor (LIFR), part of the interleukin-6 (IL-6) cytokine family, make up one such ill-defined piece of the puzzle connecting inflammation to cancer." (PMID 34395259, 2021). "The function of LIF:LIFR signaling in stemness and progression of cancers has been studied previously." (PMID 32651426, 2020). "All these data clearly indicate that LIF/LIFr and related signaling pathways are crucial in cancer initiation, implantation, growth and diffusion, in a way that recalls their function in embryo development." (PMID 30899759, 2019). "Consistent with our investigation, LIFR has been proved to be a cancer metastasis suppressor that inhibits both local invasion and metastatic colonization in a variety of tumors." (PMID 31119098, 2019). "From a clinical perspective, AZD0530 treatment presents an ideal strategy to disrupt the metastatic process in cancers associated with LIF, LIFR, or YAP1 activation." (PMID 30504771, 2018). "Mechanistically, cellular LIF appears to modulate the LIFR–YAP–focal adhesion axis to drive cancer invasion." (PMID 30504771, 2018). "Chronic or repeated exposure of cancer cells with environmental LIF can lead to downregulation of LIFR." (PMID 30504771, 2018). "On the other hand, dysregulation of LIFR has been described in a number of human cancers with diverse clinical relevance." (PMID 30504771, 2018). "A similar FR901228 treatment of the carcinoma cells further enhanced LIFR expression and LIF-dependent signaling." (PMID 16271139, 2005). "Leukemia inhibitory factor receptor (LIFR) plays an important role in cancer development, metastasis, and therapy resistance, but little is known about its biological significance, even though it was demonstrated to be associated with poor progression-free survival." (PMID 40804837, 2025). "However, in cancer contexts, parathyroid hormone-related protein (PTHrP) is known to down-regulate LIFR." (PMID 40977686, 2025). "An autocrine or paracrine loop of LIF/LIFR has been shown in different types of cancer." (PMID 38789520, 2024). "There are multiple mechanisms that converge on FGFR4 regulation, and in addition to the direct induction caused by H. pylori protein acting on cancer epithelial cells, we have now revealed a regulatory network supported by both FGF19, the natural ligand of FGFR4, and by LIF/LIFR." (PMID 37945798, 2024). "In addition, LRI-201 treatment also reversed the increment of MUC2 mRNA expression induced by LIF suggesting a potential role of the axis LIF/LIFR/FGFR4 in the onset of cancer." (PMID 37945798, 2024). "Our findings are consistent with previous studies indicating the role of LIFR in cancer biology." (PMID 39518071, 2024). "Increasingly, the focus has been on the functional exploration of LIFR in disease, but whether LIFR is correlated with the oncogenesis of certain cancer types, or just participates in more common pathways modulating cancer pathogenesis, is still unclear." (PMID 36925915, 2023). "Our results showed that LIFR expression was significantly correlated with the stromal scores in 19 types of cancers, was correlated with the immune scores in 22 types of cancers, and was especially significantly negatively correlated with the immune scores in UCEC." (PMID 36925915, 2023). "Our pan-cancer detection data provided a novel understanding of the roles of LIFR in oncogenesis." (PMID 36925915, 2023).
cancer (continued). "Recent studies indicated that the activation of LIFR and downstream STAT3 signaling maintained breast cancer cells in a dormant state and that loss of the LIFR-STAT3 axis led to enhanced proliferation of cancer cells and to bone destruction." (PMID 36925915, 2023). "Therefore, we sought a correlation between LIFR expression and various immune infiltrates across human cancers." (PMID 36925915, 2023). "This study explored LIFR expression level and prognostic landscape in pan-cancer." (PMID 36925915, 2023). "The results of these studies demonstrate that while LIF and LIFR are expressed in non-neoplastic pancreases, the two genes are differently regulated in the cancer tissues: thus, while LIFR is downregulated in PADC cancer in comparison with the adjacent tissue, LIF undergoes an opposite modulation." (PMID 36359879, 2022). "Following GSEA analysis, the LIFR were highly enriched in the calcium signaling pathway, chemokine signaling pathway, complement and coagulation cascades, focal adhesion, and pathway in cancer." (PMID 33463006, 2021). "Recent studies suggested LIF/LIFR axis as a promising clinical target for cancer therapy." (PMID 34716410, 2021). "LIFR plays both like an oncogene and like a suppressor gene in cancers." (PMID 32651426, 2020). "All this evidence indicates that LIF:LIFR axis might be an attractive target for cancer immunotherapy." (PMID 32651426, 2020). "More importantly, our data also point out that nPAK4 may be a key mediator of LIFR, an estrogen-regulated gene important for maintaining cancer cells in a dormant state." (PMID 30177834, 2019). "The results showed that LIFR was significantly downregulated in cholangio carcinoma and liver hepatocellular carcinoma although a downregulated trend of RNA expression was detected in all four types of cancers." (PMID 31119098, 2019). "Moreover, results of time-course experiments on cells treated with recombinant human LIF showed that in WT cancer cells, LIFR desensitization occurred at 30 min and is sustained up to 2 h post-LIF treatment." (PMID 30504771, 2018). "The role of EMT in the promotion of disease progression and the degree to which it affects the phenotype of cancer cells can potentially vary and may explain some of the differences in the conclusions drawn by other groups attempting to define the role of LIFR in disease progression." (PMID 37927213, 2023). "To explore LIFR expression at the pan-cancer level, we extracted LIFR expression at the gene and protein levels from public databases and evaluated its effects on survival, immune infiltration, immune-related genes, and functional pathways in various different cancers." (PMID 36925915, 2023). "Thus, the genetic alternations of LIFR were investigated in various human cancer samples." (PMID 36925915, 2023). "Furthermore, LIF is commonly upregulated in carboplatin and paclitaxel resistant cells, suggesting that LIF/LIFR overexpression might contribute to cancer chemoresistance." (PMID 35847866, 2022). "Previous reports showed that extracellular E-cadherin stabilizes the LIFR/gp130 and ErbB2 (HER2)/HER3 complexes to activate STAT3 and Erk1/2 with regard to maintaining the pluripotency of ES cells and is associated with the progression of human cancer, respectively." (PMID 33572536, 2021). "These regulatory RNAs included the anti-sense RNAs HLA-F, LIFR, PRKAR2A, ZEB1, and long intergenic non-coding RNAs (LINC) 887, 1431, 2482, as well as microRNAs (MIRs) 22HG and 3648, which are associated with viral inflammation and cancer and cellular proliferation, respectively." (PMID 33763387, 2021). "The genetic alterations of LIFR could also attribute to its diverse roles in cancer biology." (PMID 30504771, 2018).